ZMYND8 (zinc finger MYND-type containing 8)
Diseases named in the same sentence as ZMYND8 in open-access papers (continued):
Sharing a sentence is not in itself a finding about the gene and the disease.
prostate carcinoma (6 papers, 2021 to 2025). A carcinoma that arises from epithelial cells of the prostate gland. "Increased expression of ZMYND8 is associated with breast, prostate, colorectal, and cervical cancers, and it is pro-oncogenic in breast and prostate cancers." (PMID 33670804, 2021). "In contrast, lower expression of ZMYND8 is linked to breast, prostate, and nasopharyngeal cancers, and ZMYND8 exerts tumor-suppressive effects on breast and prostate cancers." (PMID 33670804, 2021). "Increased ZMYND8 expression was linked to the high-grade cervical intraepithelial neoplasia and cervical carcinoma, zebrafish prostate cancer DU145 xenografts, and prostate cancer tissues from patients." (PMID 33670804, 2021). "An increased copy number (two to six copies) of ZMYND8 has been identified in prostate cancer derived cells." (PMID 36520265, 2022). "The level of ZMYND8 expression is crucial for proliferation and invasiveness of cancer cells, and increased ZMYND8 expression is reported in colorectal, cervical, breast, and prostate cancers." (PMID 33670804, 2021). "The ZMYND8-induced suppression of invasiveness and metastasis in prostate cancer cells was demonstrated to be through cooperating with its transcriptional corepressor KDM5D." (PMID 33670804, 2021). "In zebrafish, ZMYND8 knockdown suppresses tumor angiogenesis in DU145 prostate cancer xenografts, and the re-introduction of ZMYND8 mRNA restores the tumor angiogenesis." (PMID 33670804, 2021). "ZMYND8 is induced during hypoxic conditions, and can promote angiogenesis in zebrafish, as well as in breast and prostate cancers." (PMID 33670804, 2021). "In mice injected with luciferase-expressing DU145 prostate cancer cells with ZMYND8 silencing by shRNA (shZMYND8), the luciferase signals were about five-fold higher than in those treated with the control shRNA, eight weeks after injection." (PMID 33670804, 2021). "In addition, transcriptome analyses reveal an increase in ZMYND8 expression during tumor angiogenesis in prostate cancer xenografts." (PMID 33670804, 2021). "Furthermore, ZMYND8 can induce the expression of VEGFα mRNA and promote angiogenesis in prostate cancer xenografts in zebrafish and tube formation in human umbilical vascular endothelial cell cultures." (PMID 33670804, 2021). "ZMYND8 acts as a tumor suppressor in breast and prostate cancers, and it inhibits tumor growth by promoting differentiation; inhibiting proliferation, cell-cycle progression, invasiveness, and metastasis; and maintaining the epithelial phenotype in various types of cancers." (PMID 33670804, 2021). "Knockdown of ZMYND8 increases the invasiveness of DU145 and CWR22Rv1 human prostate cancer cells in vitro, and this was also noted in an intravenous mouse xenograft model." (PMID 33670804, 2021). "In addition, ZMYND8 may promote angiogenesis in zebrafish, as well as breast and prostate cancers." (PMID 33670804, 2021). "In DU145 prostate cancer cells, in addition to KDM5C, ZMYND8 interacts with KDM5D, to act as transcriptional co-repressors, involved in regulating metastasis-linked genes." (PMID 33670804, 2021). "An increased copy number (two to six copies) of ZMYND8 is also found in DU-145, PC-3, LNCaP-FGC, BPH-1, and 22RV1 prostate cancer cells." (PMID 33670804, 2021). "ZMYND8 and KDM5D act as general negative regulators of enhancers in prostate cancer cells, and they antagonize the expression of these genes by recognizing the gene-activation-related dual-histone marker H3K4me1-H3K14ac." (PMID 33670804, 2021). "However, deletion of ZMYND8 by short hairpin RNA (shRNA) does not affect the proliferation of DU145 prostate cancer cells significantly." (PMID 33670804, 2021).
triple-negative breast carcinoma (4 papers, 2021 to 2025). An invasive breast carcinoma which is negative for expression of estrogen receptor (ER), progesterone receptor (PR), and human epidermal growth factor receptor 2 (HER2). "To investigate the role of ZMYND8 in the progression of triple-negative breast cancer, we examined its effects on cell proliferation, migration, and invasion in vitro." (PMID 41297414, 2025). "In this study, we sought to define the biological function of ZMYND8 in triple-negative breast cancer spinal metastasis (TNBC-SM) and to elucidate the molecular mechanisms underlying its aberrant accumulation." (PMID 41297414, 2025). "The previous report has identified that the Trojan lncRNA is instrumental in degrading ZMYND8, thereby promoting Triple-Negative Breast Cancer (TNBC) progression." (PMID 36064715, 2022). "To further investigate the molecular mechanism of ZMYND8 in triple-negative breast cancer spinal metastasis, we performed KEGG pathway analysis on the ZMYND8-regulated transcriptome, which suggested a potential role of ZMYND8 in modulating the WNT signaling pathway." (PMID 41297414, 2025). "In triple-negative breast cancer, TROJAN interacts with metastasis-repressing factor ZMYND8, subsequently increasing ZMYND8 degradation via the ubiquitin-proteasome pathway by repelling ZNF592, and thus enhancing cancer progression." (PMID 34446703, 2021).
bladder cancer (3 papers, 2023 to 2025). "ZMYND8 increased cell viability and colony formation, migrative ability in bladder cancer." (PMID 37215134, 2023). "FBXW7 targeted an epigenetic regulator ZMYND8 for ubiquitination and degradation in bladder cancer." (PMID 37215134, 2023).
glioma (3 papers, 2023 to 2024). A benign or malignant brain and spinal cord tumor that arises from glial cells (astrocytes, oligodendrocytes, ependymal cells). "The use of pharmaceutical inhibitor AGI-5198 with IDH mutant patient-derived cultured glioma cells has demonstrated the downregulation of essential epigenetic reader Zinc Finger MYND-Type Containing 8 (ZMYND8)." (PMID 39596840, 2024).
hepatocellular carcinoma (3 papers, 2021 to 2025). A malignant tumor that arises from hepatocytes. "It has been reported that ZMYND8 is overexpressed at protein and mRNA levels in considerable amount of hepatocellular carcinoma (HCC) cases." (PMID 36520265, 2022).
nasopharyngeal carcinoma (3 papers, 2021 to 2025). A carcinoma arising from the nasopharyngeal epithelium. "In breast and nasopharyngeal cancers, ZMYND8 is down-regulated and its low expression correlates with increased invasiveness and poor prognosis." (PMID 35562985, 2022). "Overall, ZMYND8 appears to act as a tumor suppressor in breast, prostate, and nasopharyngeal cancers." (PMID 33670804, 2021). "In 190 patients with nasopharyngeal carcinoma, low ZMYND8 expression was correlated with late T stage, presence of lymph node metastasis, advanced stage, and poor overall patient survival." (PMID 33670804, 2021). "In contrast, downregulation of ZMYND8 is also reported in breast, prostate, and nasopharyngeal cancers." (PMID 33670804, 2021).
colorectal cancer (2 papers, 2021 to 2025). A primary or metastatic malignant neoplasm that affects the colon or rectum. "Mutation frequency of ZMYND8 was 19% in mismatch repair-deficient colorectal cancers." (PMID 33670804, 2021). "Analyses of the Cancer Genome Atlas (TCGA) and Gene Expression Omnibus (GEO) database suggested that high expression of ZMYND8 was closely correlated with poor overall and disease-free survival in 174 colorectal cancer patients." (PMID 33670804, 2021).
glioblastoma (2 papers, 2021 to 2025). The most malignant astrocytic tumor (WHO grade IV). "ZMYND8 can recognize mutated histone H3.3 (H3.3G34R) detected in pediatric glioblastomas; however, it is unclear whether ZMYND8 can also regulate tumor biology by recognizing posttranslational modifications of nonhistone proteins." (PMID 33593912, 2021).
neuroblastoma (2 papers, 2012 to 2022). Neuroblastoma (NB) is the most common solid, extracranial childhood tumor. "Using quantitative RT-PCR (qRT-PCR), we measured the endogenous expression of Zmynd8as, Brd1as, and the various isoforms of Zmynd8 and Brd1 in undifferentiated mESCs (UN), NPs (NP), and N2A (Neuro-2A), a mouse neuroblastoma cell line." (PMID 22937057, 2012). "Thus, ZMYND8 could be employed to program the neuroblastoma cells towards a differentiated phenotype and has a huge therapeutic potential." (PMID 36064715, 2022). "Previously we observed that ZMYND8 remarkably alters the transcription of several neuronal differentiation markers, including MAPT, upon ATRA-treatment in neuroblastoma cells." (PMID 36064715, 2022).
ovarian carcinoma (2 papers, 2012 to 2020). A malignant neoplasm originating from the surface ovarian epithelium. "By analyzing the TCGA database and performing HR repair screening, we demonstrated that three BRD-containing proteins, BRD9, ASH1L, and ZMYND8, positively regulate HR, and the mutations of these three BRD-containing proteins are associated with HR-deficient mutational signatures in ovarian cancer." (PMID 32457312, 2020).
acute myeloid leukemia (1 paper, 2021). Acute myeloid leukemia (AML) is a group of neoplasms arising from precursor cells committed to the myeloid cell-line differentiation. "In addition, the ZMYND8-v-rel reticuloendotheliosis viral oncogene homolog A (avian) (RELA) chimeric transcripts were reported in a four-month-old patient with acute erythroid leukemia, a type of acute myeloid leukemia (AML)." (PMID 33670804, 2021).
autism spectrum disorder (1 paper, 2025). A spectrum of developmental disorders that includes autism, and Asperger syndrome. "Additionally, we observed ectodermal EtOH-induced alterations in several genes, such as LHX2, SHANK2, TRIO, ZMYND8, ARX, NRXN3 and SEMA5A, that have also been associated with autism spectrum disorder (ASD) (SFARI Gene Database, 2024; accessed: 1, August, 2024)." (PMID 40401629, 2025).
cervical cancer (1 paper, 2021). A primary or metastatic malignant neoplasm involving the cervix. "Increased expression of ZMYND8 is linked to breast, prostate, colorectal, and cervical cancers." (PMID 33670804, 2021). "Overall, these results indicate that ZMYND8 may have a crucial role in the tumorigenesis of breast, prostate, colorectal, and cervical cancers." (PMID 33670804, 2021).
colitis (1 paper, 2021). Inflammation of the colon. "The in vivo relevance of our findings was evident in mouse models of colitis and obesity, which resulted in the aggravated disease upon conditional ablation of Zmynd8 in macrophages." (PMID 34764296, 2021).
colon cancer (1 paper, 2022). "Besides, ZMYND8 and SREBP2 drive the enhancer-promoter interaction to facilitate the recruitment of Mediator complex, thus upregulating MVA pathway genes and enhancing colon cancer progression." (PMID 36357379, 2022).
hyperglycaemia (1 paper, 2020). "Interestingly, BRD2, which contained a DMR associated with both 1-h and 2-h PG, is known to interact with ZMYND8 and was previously reported by Houde and colleagues to be associated with maternal hyperglycaemia." (PMID 33151971, 2020).
inflammatory bowel disease (1 paper, 2021). A spectrum of small and large bowel inflammatory diseases of unknown etiology. "We, therefore, set up an inflammatory bowel disease (IBD) model in Zmynd8 cKO mice by treating them with DSS." (PMID 34764296, 2021).
leukemia (1 paper, 2025). A malignant (clonal) hematologic disorder, involving hematopoietic stem cells and characterized by the presence of primitive or atypical myeloid or lymphoid cells in the bone marrow and the blood. "Previous findings also suggested that ZMYND8 is essential for AML survival by binding to the ET domain of BRD4 through its chromatin reader domain, thereby sustaining leukemia growth." (PMID 40223119, 2025).
lymph node metastasis (1 paper, 2025). "Clinically, elevated ZMYND8 expression is associated with advanced tumor stage, lymph node metastasis, spinal involvement, and diminished survival in TNBC patients." (PMID 41297414, 2025).
migraine (1 paper, 2024). "Based on our own RNA-sequencing data, genes previously known to link with migraine through genome-wide analysis or various migraine models, Crebbp, Trpm3, Zmynd8 and Akt1 are among the potential candidate genes that have especially caught our interest." (PMID 39390364, 2024).
myeloma (1 paper, 2025). "To determine the role of ZMYND8 in the progression of myeloma, we investigated its effects on cell proliferation, invasion, and apoptosis in vitro." (PMID 40347515, 2025). "Our future studies will focus on identifying and developing specific ZMYND8 agonists to investigate their potential effects on myeloma." (PMID 40347515, 2025).
Photophobia (1 paper, 2024). Excessive sensitivity to light with the sensation of discomfort or pain in the eyes due to exposure to bright light. "Future studies on understanding the role of Zmynd8 in photophobia and the mechanism underlying its relation with SFKs may prove to be important." (PMID 39390364, 2024). "When mRNA levels of Crebbp, Trpm3, Zmynd8 and Akt1 were compared between the two sexes, female photophobia mice showed significant lower levels than that of males." (PMID 39390364, 2024).
tumor (28 papers, 2017 to 2025). "ZMYND8 is implicated in occurrence of cancers in a manner dependent on tumor typeI; its expression level is varied among different type of tumors." (PMID 36520265, 2022). "ZMYND8 is a putative chromatin reader and has a tumor-suppressive role by suppressing the metastasis-linked genes and reinstating the epithelial state of the cells." (PMID 33323928, 2020). "Consistently, sensitizing the cancer cells with ZMYND8 followed by doxorubicin treatment led to tumor regression in vivo and revert back the phenotypes associated with drug resistance and stemness." (PMID 33323928, 2020). "Taken together, these findings indicate that ZMYND8 overexpression enhances the efficacy of CFZ in suppressing MM tumor growth." (PMID 40347515, 2025). "ZMYND8 overexpression significantly inhibited the proliferation and invasion of MM cells and effectively suppressed tumor growth in mice, whereas ZMYND8 knockdown had the opposite effects." (PMID 40347515, 2025). "Several studies have demonstrated a tumor suppressive role of ZMYND8 by suppression of superenhancer-regulated gene expression." (PMID 40223119, 2025). "In conclusion, our study elucidated the precise mechanism by which ZMYND8 exerts its tumor‐suppressive effects in MM." (PMID 40347515, 2025). "To evaluate the in vivo therapeutic efficacy of CFZ upon ZMYND8 overexpression, we established xenograft tumor models derived from H929 cells." (PMID 40347515, 2025). "Upregulating the expression of ZMYND8 under CFZ treatment effectively mitigated MM tumor progression." (PMID 40347515, 2025). "Statistical analysis revealed that ZMYND8 upregulation increased both the incidence of spinal metastasis and tumor burden in mice." (PMID 41297414, 2025). "The low expression of ZMYND8 in normal tissues and its high expression in the tumor microenvironment (TME) suggest the potential for tumor-targeted blockade therapy against ZMYND8." (PMID 41297414, 2025). "CFZ monotherapy exhibited moderate therapeutic efficacy against MM, and ZMYND8 overexpression significantly suppressed tumor proliferation and augmented the efficacy of CFZ in MM." (PMID 40347515, 2025). "To exclude a role of ZMYND8–mediated immune response in tumor initiation, we compared the initiation frequency of SC and ZMYND8-KO 4T1 tumors in both immunocompromised NSG mice and immunocompetent BALB/c mice using limiting dilution assay." (PMID 38488001, 2024). "In this study, we showed that ZMYND8 attenuated oxidative stress and ferroptosis in aldehyde dehydrogenase–high (ALDHhi) BCSCs to promote tumor initiation in vitro and in mice." (PMID 38488001, 2024). "Another multifaceted protein that acts either as a tumor promoter or suppressor in various tissues is Zinc Finger MYND-Type Containing 8 (ZMYND8), exhibiting diverse effects on cell proliferation, angiogenesis, invasion, and metastasis." (PMID 38539439, 2024). "ZMYND8 overexpression resulted in the downregulation of tumor-promoting genes by repressing their poised promoters in association with KDM5C and EZH2." (PMID 36674511, 2023). "In line with the negative regulation of MST1/2 on ZMYND8, this analysis also revealed that the expression levels of ZMYND8 were higher in oxaliplatin-treated tissues than in untreated tumor tissues." (PMID 35290241, 2022). "Aberrantly expressed FBXW7 mediates ZMYND8 ubiquitination degradation and enhances tumor progression and stemness in BCa45." (PMID 36147463, 2022). "ZMYND proteins which are recognized to be tumor suppressors in both hematopoietic and solid neoplasms, ZMYND8 and 11 possess functional domains to recognize histone code or recruit histone modifying enzymes, for example lysine demethylases." (PMID 36520265, 2022). "In cancer cells, ZMYND8 modulates histone methylation and acetylation, regulating the expression of oncogenes and tumor suppressors." (PMID 35562985, 2022).